G6PD (glucose-6-phosphate dehydrogenase)
Diseases named in the same sentence as G6PD in open-access papers (continued):
Sharing a sentence is not in itself a finding about the gene and the disease.
diabetes (continued). "Altered G6PD activity is associated with pathophysiology, such as autophagy, insulin resistance, infection, inflammation, as well as diabetes and hypertension." (PMID 31500396, 2019). "Given the large effects of the G6PD G202A variant on HbA1c levels, we sought to investigate the impact this variant would have on diabetes detection if using HbA1c as a screening tool." (PMID 28898252, 2017). "Improper management of diabetes mellitus caused a decrease in G6PD activity and an increase in protein oxidation markers: protein carbonyl group and total thiol group." (PMID 26317017, 2013). "Given the lower levels of HbA1c in G6PD carriers with a T2D diagnosis which could lead to delays in treatment escalation, we sought to investigate the effect of G6PD deficiency allele carrier status on diabetes complications." (PMID 41022122, 2025). "Although there may be an interaction between plasma G6PD level and diabetes, our study is the first study to investigate the associated factors of urine G6PD activity in T2DM." (PMID 39140974, 2024). "Elevated levels of miR-7977 may target and degrade G6PD, thereby inhibiting albumin-induced autophagy in diabetes and potentially playing a crucial pathogenic role in the development of DKD." (PMID 39140974, 2024). "Several studies have suggested that G6PD-deficient individuals may be more predisposed to specific autoimmune diseases, infections and diabetes mellitus." (PMID 37753082, 2023). "Moreover, the altered or deficient activity of G6PD is related to different pathologies such as insulin resistance, diabetes, anemia, hypertension, autophagy, infection, and inflammation." (PMID 35805067, 2022). "In addition, glycosylation of proteins and hyperglycemia is higher in diabetes and oxidative stress, causing a decrease in the activity of G6PD and its protective mechanisms, particularly in patients with inherited G6PD deficiency." (PMID 35805067, 2022). "In addition,it will also be interesting to evaluate the association of PC level with the severity of diabetes, especially in G6PD-deficient subjects, and monitor the efficacy of antioxidants supplementation in controlling the PC level." (PMID 34949182, 2021). "Additionally, interactions have been reported between diabetes and a deficiency in glucose-6-phosphate dehydrogenase (G6PD), the enzyme that catalyzes the first step of the pentose phosphate pathway." (PMID 34299508, 2021). "Altered G6PD status is implicated in many cellular pathophysiological processes and diseases, including hypoxia, inflammation, microbial infection, sepsis, pulmonary vessel dilation, diabetes, hypertension, kidney disease, and brain injuries." (PMID 31500396, 2019). "Hence, G6PD displays a cytoprotective action against oxidative stress, i.e., a key pathological factor associated with diabetes." (PMID 30513672, 2018). "This may also have important implications for the management of diabetes, with carriers of the HbA1c-lowering G6PD allele requiring adjusted (lower) HbA1c treatment targets." (PMID 28898252, 2017). "However, whether there is a causal relationship between G6PD activity and blood lipids in diabetes needs further study." (PMID 39140974, 2024). "Moreover, G6PD deficiencies are highly correlated with the prevalence of diabetes." (PMID 34299508, 2021). "Oxidative Stress, an imbalance in the pro-oxidant/antioxidant homeostasis, occurs in many physiological and non-physiological processes and several human diseases, including diabetes mellitus (DM) and glucose-6-phosphate dehydrogenase (G6PD) deficiency." (PMID 34949182, 2021). "TLR4-induced diabetic neuropathic pain is also relieved by glucose-6-phosphate dehydrogenase (G6PD)." (PMID 40002826, 2025). "The pathophysiologic roles for G6PD have been confirmed in the progression of multiple diseases (e.g. diabetes, cancer, and virus infection)." (PMID 40963919, 2025).
diabetes (continued). "Although G6PD activity is known to be influenced by various factors such as infection and diabetes mellitus, only age and gender were included as covariates in the analysis due to limitations in the available clinical records." (PMID 41374996, 2025). "Diabetes induction led to a decline in hepatic G6PD content, an enzyme crucial for glucose metabolism." (PMID 40603345, 2025). "Studies in experimental type-2 diabetes models have shown that diabetes decreases G6PD enzyme activity." (PMID 39726786, 2024). "A significant number of studies have unveiled the roles of G6PD in various aspects of physiology other than erythrocytic pathophysiology, such as diabetes, cardiovascular disease, and neurodegeneration." (PMID 36231003, 2022). "Of note, the diabetes-afflicted rats injected with BMSCs + CeO2-derived IPCs revealed a significant decline (p < 0.05) in liver G6PD activity relative to those injected with ADSCs + Se/Ti (III)-derived IPCs or BMSCs + Se/Ti (III)-derived IPCs." (PMID 36248064, 2022). "Abnormal behavior of G6PD is related to a variety of pathological processes and diseases, including inflammation, diabetes, and tumors." (PMID 34150630, 2021). "Insulin stimulates transcription of malic enzyme in the liver and situations of insulin resistance or diabetes reduce G6PD activity." (PMID 33800837, 2021). "In support of these observations, significant decreases in G6PD activity were observed in aortic endothelial cells and animal tissues due to hyperglycemia or diabetes." (PMID 33050491, 2020). "In fact, it is well-known that a deficit of glucose-6-phosphate dehydrogenase exit in RBCs of patients with diabetes, thus leading to the reduction of the glycolysis metabolites in these cell." (PMID 32471219, 2020). "For example, fisetin has an inhibitory effect, while morin has a stimulatory effect on glucose 6 phosphate dehydrogenase and the literature states that they both improve diabetes." (PMID 31480505, 2019). "The level and activity of hepatic enzymes, such as glucose-6-phosphate dehydrogenase, decreases with diabetes." (PMID 31480505, 2019). "In diabetes the enzyme glucose-6-phosphate dehydrogenase (G6PD) is inhibited; therefore, the entire defense mechanism becomes compromised and lower amounts of enzymatic-cofactor NADPH are formed and available." (PMID 28325998, 2017). "A state of oxidative damage is attained due to the relatively low levels (response to diabetes) of glucose-6-phosphate dehydrogenase which is the key enzyme in the synthesis of this pentose sugar (pentose phosphate pathway)." (PMID 27003006, 2016). "Most frequency of distribution of chronic disease type was hypertension (47.96%) and then diabetes (14.47%) and the least was related to other disease (colic, asthma, G6PD, lupus) equal to 1.8%." (PMID 24999131, 2014). "G6PD activity can be taken as a biomarker of oxidative stress and poor glycemic control in type 2 diabetes mellitus patients." (PMID 26317017, 2013). "It was found that hyperglycemia of diabetes mellitus and high glucose levels decrease the activity of G6PD and the inhibition was through the increase in adenylate cyclase activity which in turn increases cAMP levels within the cell." (PMID 26317017, 2013). "G6PD deficient men had 1.37 [95% CI: 1.01, 1.86] higher odds of developing diabetes-related microvascular complications than non-carriers." (PMID 41022122, 2025). "We report a simple clinical algorithm that enables health care systems to identify people who may benefit from G6PD genotyping and glucose-based diabetes monitoring." (PMID 41362833, 2025). "However, it seems that the progression of diabetes eventually leads to a decrease in G6PD activity, as we found in this study." (PMID 39519313, 2024). "Future studies are needed to clarify tissue-specific G6PD contribution to arterial stiffening in diabetic subjects, and its possible role for the development of new therapeutic agents able to reduce the cardiovascular burden of diabetes mellitus." (PMID 37741911, 2024).
diabetes (continued). "A further contribution to the G6PD inhibition may be related to the increased glucagon level, which is always present to some extent in diabetes, given that it is known that the injection of glucagon into experimental animals reduces G6PD activity." (PMID 36431166, 2022). "Investigating whether RIP140 regulates G6PD expression in other tissues could be important for diseases related to metabolic disorders, such as obesity, and related diseases, such as diabetes." (PMID 35806424, 2022). "Also, screening of G6PD enzyme activity should be considered in patients newly diagnosed with diabetes, especially in boys, considering the ethnic origin of the patient, to reduce the risk of hemolysis." (PMID 36008815, 2022). "Regarding the oxidative stress status, we observed a 5.5 to 6-fold increase in the PC levels in patients with diabetes and in G6PD-deficient subjects more than in non-diabetic subjects with sufficient G6PD levels (p<0.001)." (PMID 34949182, 2021). "PC level in patients with diabetes and in G6PD-deficient subjects was 5.5 to 6-fold higher than in non-diabetic subjects with sufficient G6PD levels (p<0.001)." (PMID 34949182, 2021). "A study using a cell culture model of diabetes observed that the increased activity of G6PD restored redox balance in endothelial cells exposed to high glucose levels, where high glucose levels had previously decreased G6PD and increased levels of oxidative stress." (PMID 32937931, 2020). "Recently, resveratrol has been found to improve G6PD activity in an animal model of diabetes." (PMID 30513672, 2018). "This investigation aimed to study G6PD activity as a biomarker of oxidative stress and correlate its activity to protein oxidation markers; protein carbonyl group concentration and total thiol group content in type 2 diabetes mellitus." (PMID 26317017, 2013). "In the present investigation, the effects of diabetes mellitus on the activity of G6PD and markers of protein oxidation, protein carbonyl group concentration, and total thiol group content in patients with type 2 diabetes mellitus under poor glycemic were studied." (PMID 26317017, 2013). "In addition, Obtained results revealed that, in diabetics, G6PD activity negatively correlated to protein carbonyl and HbA1C (r = −0.77 and −0.65, resp)." (PMID 26317017, 2013). "It has been observed that defects in the G6PD gene correlate with diabetes and a more recent study proposed that alterations in genes controlling both insulin secretion and G6PD-mediated antioxidant defences may contribute to a predisposition to diabetes." (PMID 18485212, 2008). "Therefore, diabetes was unlikely to be a confounding factor in the association between adequate hemodialysis and G6PD activity levels." (PMID 25261071, 2014). "Future research should include adjustments for potential confounders, such as the presence of diabetes mellitus and ECOG performance status, to validate the predictive value of G6PD activity for gastric cancer staging." (PMID 41374996, 2025). "Contrastingly, the more erythrocytic variants that a person had did not increase the risk of diabetes, as some erythrocytic variants, such as glucose-6-phosphate dehydrogenase (G6PD), could lower HbA1c independent of glucose concentration and lead to a missed diagnosis." (PMID 32923278, 2020). "Future studies using therapeutic approaches that increase G6PD and/or inhibit PKA in animal models of diabetes should provide further insights into the development of new possible treatments." (PMID 23185302, 2012). "According to previous studies, infection, diabetes mellitus, hemolytic anemia, TNM stages and chemotherapy status could vary G6PD activity." (PMID 41514554, 2025). "Despite prior studies showing lower G6PD activity in diabetes mellitus, the prevalence of diabetes was not significantly different between our two groups." (PMID 25261071, 2014).
diabetes (continued). "In addition, Nsd2 is downregulated in diabetes mellitus type 2 and has been shown to play a role in insulin secretion and glucose metabolism by regulating hexokinase 2 (HK2) and glucose-6-phosphate dehydrogenase (G6PD)." (PMID 38818037, 2024). "However, certain endocrine and metabolic conditions, such as hyperaldosteronism and diabetes, can inhibit the G6PD enzyme without any genetic defect." (PMID 39726786, 2024). "But whether decreased G6PD is the major defect in diabetes as compared to other antioxidant enzymes has not previously been addressed." (PMID 29979777, 2018). "Here, we show that TLQP-21 could promote G6PD/NADPH generation and upregulate the intracellular anti-oxidant system without obvious side effects, suggesting its potential for diabetes therapy." (PMID 24278172, 2013).
thalassemia (74 papers, 2007 to 2025). An inherited blood disorder characterized by a decreased synthesis of one of the polypeptide chains that form hemoglobin. "The coexistence of gallstone disease with HS and related hemolytic disorders like thalassemia and glucose-6-phosphate dehydrogenase (G6PD) deficiency represents a rare but clinically significant phenomenon." (PMID 41356983, 2025). "In vitro studies reported that under oxidative stress conditions, parasite growth is significantly inhibited in RBCs derived from individuals carrying thalassemia and glucose-6-phosphate dehydrogenase (G6PD) mutations." (PMID 38427625, 2024). "It is unclear how the intracellular levels of FAD/FMN are regulated and how it is associated with thalassemia and G6PD mutations." (PMID 38427625, 2024). "The mean corpuscular hemoglobin (pg) of the test sample should be taken into account, as very low values (as seen in thalassemia and iron deficiency) will overestimate the activity of G6PD." (PMID 39436963, 2024). "We therefore typed individuals for α-thalassaemia, blood group O, G6PD deficiency and ATP2B4 alleles, and carried out the same set of analysis as above for each genotype." (PMID 37310872, 2023). "This can be clearly seen with hemoglobinopathy gene polymorphisms such as sickle cell, thalassemia or glucose-6-phosphate dehydrogenase (G6PD) which offer resistance to infection of RBCs by Plasmodium and reduced clinical severity when infection does occur." (PMID 36146602, 2022). "Compared with normal newborns after controlling for thalassemias and hemoglobinopathies, G6PD-deficient patients with the G6PD ViangchanG871A mutation exhibited elevated reticulocyte counts (5.82 ± 1.73%, p < 0.001)." (PMID 36419023, 2022). "The proportion of G6PD variants was comparable across the groups (p = 0.294), while the proportion of thalassemia variants differed across the groups (p = 0.025)." (PMID 36186473, 2022). "We investigated the association of alpha‐thalassemia deletion and G6PD deficiency [G6PDA‐] with stroke risk as stratified by TCD velocity status among Nigerian children with sickle cell anemia." (PMID 33938598, 2021). "Alpha‐thalassemia (the α‐3.7 globin gene deletion) was determined by multiplex gap‐PCR, while G6PD polymorphisms (202G > A and 376A > G) were genotyped using restriction fragment length polymorphism—polymerase chain reaction." (PMID 33938598, 2021). "There were some differences of the distribution of thalassemia and G6PD mutations among eight counties in Meizhou." (PMID 31793705, 2020). "As a mature technology, reverse dot blot (RDB) technology has been successfully applied to the genotypic diseases such as thalassemia and Glucose-6-phosphate dehydrogenase(G6PD) deficiency." (PMID 31382905, 2019). "Some examples of pathologies where increased oxidative stress activates Ca2+ cation channels and thereby induces PS exposure and eryptosis are sickle cell anemia, thalassemia, G6PD, iron deficiency, chronic kidney disease, and diabetes." (PMID 28210260, 2017). "Common red blood cell polymorphisms (ie, hemoglobin S, glucose-6-phosphate dehydrogenase, and α-thalassemia) were the only ones to be associated with all 3 measures of transmission intensity and the first principal component." (PMID 28541483, 2017). "Sickle cell trait, thalassemia trait, and G6PD-deficient individuals are known to have a selective advantage with respect to malarial infections." (PMID 28210260, 2017). "They included unavailable platelets counts, B12 levels, folate levels, SCD, thalassemia, glucose-6-phosphate dehydrogenase (G6PD) deficiencies, and bone marrow biopsies." (PMID 28948119, 2017). "In this country, couples who plan to marry undergo blood test to investigate if they are carriers of any of the genetic blood disorders: thalassemia, sickle cell anemia and Gloucose-6-phosphate dehydrogenase deficiency (G6PD)." (PMID 24742222, 2014).